SPP1 (secreted phosphoprotein 1)
Diseases named in the same sentence as SPP1 in open-access papers (continued):
Sharing a sentence is not in itself a finding about the gene and the disease.
leukemia (15 papers, 2011 to 2025). A malignant (clonal) hematologic disorder, involving hematopoietic stem cells and characterized by the presence of primitive or atypical myeloid or lymphoid cells in the bone marrow and the blood. "SPP1 promotes the chemotherapy resistance of leukemia and solid tumors." (PMID 38956502, 2024). "The decreased SPP1 levers were observed in BC, kidney cancer, sarcoma and leukemia." (PMID 33324676, 2020). "Therefore, SPP1 is emerging as a novel target for the treatment of leukemia and solid tumors." (PMID 38956502, 2024).
metastatic carcinoma (15 papers, 2011 to 2025). A carcinoma which has spread from the original site of growth to another anatomic site. "Among the few studies focusing on the role of molecules in this process, osteopontin (OPN), also known as secreted phosphoprotein 1, it is implicated in the control and regulation of local inflammation and immunity, and it is linked with metastatic cancer prognosis and overall survival." (PMID 37893935, 2023). "The outgoing interaction strength of SPP1 + TAMs was significantly higher than the incoming interaction strength in metastatic carcinoma." (PMID 38365757, 2024). "We reveal the interaction of SPP1 + TAMs with CD8 + exhausted T cells in metastatic cancer." (PMID 38365757, 2024). "There are five genes (BGN, THBS2, SPARC, CDH11 and SPP1) in metastatic cancer tissues that are significantly higher than non‐metastatic cancer tissue at the transcriptomics level, while only BGN and THBS2 were significant difference in protein expression between metastatic and non‐metastatic cases." (PMID 36377223, 2022). "SPP1 was found in four signatures that were derived from ER-negative or TNBC or metastatic cancers." (PMID 29699511, 2018). "CD8 + T exhausted cells in metastatic cancer may be regulated by SPP1 + TAMs." (PMID 38365757, 2024). "We speculate that CD8 + T exhausted cells may be regulated by SPP1 + TAMs in metastatic cancer." (PMID 38365757, 2024).
chronic obstructive pulmonary disease (14 papers, 2019 to 2025). A chronic and progressive lung disorder characterized by the loss of elasticity of the bronchial tree and the air sacs, destruction of the air sacs wall, thickening of the bronchial wall, and mucous accumulation in the bronchial tree. "Single-cell studies reveal significant alterations in inflammatory pathways in cardiac arrhythmias, particularly noting an expansion of inflammatory monocytes and secreted phosphoprotein 1 (SPP1+) macrophages." (PMID 40900730, 2025). "This study uncovers potential genetic drivers of pathological events in cardiac arrhythmias, particularly the SPP1+ macrophage-mediated inflammation and fibrosis." (PMID 40900730, 2025). "In chronic obstructive pulmonary disease (COPD), SPP1 expression is markedly increased, particularly in airway cells and antigen-presenting cells of patients with emphysema." (PMID 41293726, 2025). "SPP1 is elevated in the distal airways of subjects with chronic obstructive pulmonary disease (COPD), including increased expression in goblet and club cells." (PMID 40559389, 2025). "Another study demonstrated that inhibition of SPP1 blocked the PIK3C3-AKT-mTOR pathway, resulting in the alleviation of chronic inflammation and mediating Th17/Treg differentiation in chronic obstructive pulmonary disease (COPD)." (PMID 38919629, 2024).
Duchenne muscular dystrophy (14 papers, 2013 to 2025). Duchenne muscular dystrophy (DMD) is a neuromuscular disease characterized by rapidly progressive muscle weakness and wasting due to degeneration of skeletal, smooth and cardiac muscle. "A SNP in SPP1 promoter has been shown to influence disease severity in Duchenne muscular dystrophy: rare allele of rs28357094 yields less SPP1 protein, causing greater phenotype." (PMID 31879711, 2019). "Two genetic modifiers of Duchenne Muscular Dystrophy implicate the transforming growth factor β (TGFβ) pathway, osteopontin encoded by the SPP1 gene and latent TGFβ binding protein 4 (LTBP4)." (PMID 29065150, 2017). "A study of Duchenne muscular dystrophy found an rs28357094 polymorphism, which lies in the gene promoter of SPP1, to be associated with GC response." (PMID 28620344, 2017). "Furthermore, SPP1 gene polymorphisms have been identified as being associated with GC responsiveness in boys with Duchenne muscular dystrophy; however, a larger validation study published after we began our work did not confirm the association." (PMID 28620344, 2017). "Amongst others, misregulation in the level of SPP1 has been reported as possible biomarker for Duchenne Muscular Dystrophy and cardiovascular events." (PMID 30188931, 2018). "Furthermore, a single nucleotide polymorphism upstream of the transcriptional start site of the osteopontin (SPP1) gene has been identified as a strong genetic modifier of disease severity in Duchenne muscular dystrophy." (PMID 30808406, 2019). "For example, SPP1 is a known modifier of disease severity in Duchenne muscular dystrophy." (PMID 24455711, 2013). "Indeed, in mdx models (a widely used mouse model for Duchenne muscular dystrophy), Spp1 ablation decreases active TGFβ and improves fibrosis, whereas in the mdxD2 model, a more severe dystrophic model characterised by constitutively high TGFβ signalling, Spp1 ablation has minimal impact." (PMID 40395129, 2025). "In summary, our data highlight SPP1 rs11730582 as a genetic modifier of the long-term effect of GCs treatment in Chinese patients with Duchenne muscular dystrophy, but do not indicate a previously reported association between LTBP4 haplotype and disease progression." (PMID 32849198, 2020).
experimental autoimmune encephalomyelitis (14 papers, 2010 to 2025). An autoimmune demyelinating disease of the central nervous system that is produced experimentally in animals by the injection of homogenized brain or spinal cord in Freund's adjuvant. "Spp1 upregulation has been observed in response to injury in different animal models of CNS trauma, in experimental autoimmune encephalomyelitis (EAE), and in microglia/macrophages and astrocytes during cuprizone-induced demyelination." (PMID 36499195, 2022).
lung diseases (14 papers, 2011 to 2025). "Here, we review the proposed mechanisms by which SPP1 contributes to the development of lung disease, with an emphasis on ILD." (PMID 40559389, 2025). "SPP1 and the Osteopontin it encodes are crucial factors influencing ECM dynamics and play a significant role in tumor diseases, cardiovascular diseases, pulmonary diseases, chronic kidney disease, and osteoarthritis." (PMID 41293726, 2025). "In conclusion, SPP1 represents a unifying effector across diverse forms of lung diseases, particularly ILD." (PMID 40559389, 2025). "A deeper understanding of SPP1 biology may pave the way for personalized interventions and improved outcomes for patients suffering from these debilitating lung diseases." (PMID 40559389, 2025). "Interestingly, SPP1+-recruited macrophages are also present in allergic asthmatic patients, suggesting a potential conserved mechanism of lung injury and repair across a spectrum of lung diseases." (PMID 40559389, 2025). "Serum SPP1 levels are also significantly higher in individuals with pleural mesothelioma—a malignancy closely linked to asbestos exposure—than in those exposed to asbestos but without lung disease." (PMID 40559389, 2025). "In addition, SPP1 may be a useful biomarker for the development and progression of fibrotic lung diseases." (PMID 26955063, 2016). "The role of MMP12, SPP1, AHRR and CYP1B1 in cigarette smoke-related lung diseases have been well described and studied." (PMID 24663285, 2014). "SPP1 (Osteopontin) serves as a principal regulator of aberrant ECM remodeling and is prevalent in numerous conditions, including cancer, cardiovascular illness, pulmonary disease, chronic renal disease, and osteoarthritis." (PMID 41293726, 2025).
pulmonary hypertension (14 papers, 2011 to 2025). Increased pressure within the pulmonary circulation due to lung or heart disorder. "Further study of the molecular mechanism of SPP1 in pulmonary hypertension will be beneficial to the majority of patients." (PMID 33816621, 2021). "Secreted phosphoprotein 1 (SPP1, also known as osteopontin or OPN), a key mediator secreted by SMCs, contributes to the genesis and progression of pulmonary hypertension by enhancing PVSMC proliferation." (PMID 32714978, 2020).
dilated cardiomyopathy (13 papers, 2011 to 2025). Cardiomyopathy which is characterized by dilation and contractile dysfunction of the left and right ventricles. "Both the SPP1 genotype and glucocorticoids use could have some negative impact on the development of dilated cardiomyopathy." (PMID 34451895, 2021).
glaucoma (13 papers, 2014 to 2025). Increased pressure in the eyeball due to obstruction of the outflow of aqueous humor. "In a similar way, SPP1 overexpression mediated by adeno-associated virus preserved retinal ganglion cells and vision in a mouse model of glaucoma induced by IOP elevation using microbeads injection." (PMID 39000104, 2024). "Importantly, GAS6 and SPP1 showed high diagnostic ability of glaucoma, which in combination allowed for discriminating glaucoma patients from control individuals with an area under the curve of 76.1% and a sensitivity of 65.6% and a specificity of 87.7%." (PMID 39000104, 2024). "Animal experimental studies have found that SPP1 is significantly increased in the aqueous humor of dogs with a primary angle-closure glaucoma (PACG) model." (PMID 40486511, 2025). "We focused on GAS6 and SPP1 because these validated dysregulated proteins in glaucoma by WB were among the most upregulated proteins found in aqueous humor." (PMID 39000104, 2024). "Our findings revealed not only the interesting potential of sEVs aqueous humor for the determination of biomarkers with diagnostic interest but also the usefulness of GAS6 alone or in combination with SPP1 for glaucoma diagnosis." (PMID 39000104, 2024). "The combination of GAS6 and SPP1 increased the AUCs to 76.1% and 68.7% for discriminating glaucoma patients from ICL or from cataracts patients, respectively, with a sensitivity of 65.6%, and a specificity of 87.7% and 88.5%, respectively." (PMID 39000104, 2024). "SPP1 expression in α-retinal ganglion cells exposed to chronic IOP elevation promoted neuronal resiliency in glaucoma models." (PMID 39000104, 2024). "To this end, we focused on GAS6 and SPP1, which exhibited a high upregulation in sEVs from aqueous humor from cataracts and/or glaucoma patients and were validated by WB in the total content of aqueous humor." (PMID 39000104, 2024). "Remarkably, GAS6 and SPP1 were able to distinguish glaucoma patients from ICL and cataract patients with high diagnostic ability." (PMID 39000104, 2024). "Using 162 individual aqueous humors samples (39 ICL, 92 cataracts, and 31 glaucoma samples), the levels in aqueous humors of GAS6 and SPP1 significantly discriminated glaucoma patients from ICL or cataracts patients (control samples)." (PMID 39000104, 2024). "Lower SPP1 levels were initially reported in glaucoma patients as compared to cataract patients, whereas, more recently, increased SPP1 concentration was found in glaucoma patients as compared to cataract patients." (PMID 39000104, 2024). "The clear neuroprotective effect and the apparent safety even in long-term expression studies make SPP1 as an attractive candidate molecule for neuroprotective therapy in glaucoma." (PMID 37160307, 2023). "We sought to screen and identify small molecules that increase SPP1 expression as an adjuvant glaucoma treatment." (PMID 37160307, 2023). "Assessing SPP1 levels in a larger cohort of patients with varying glaucoma severities, varying treatment interventions, and over an extended treatment course would help refine the diagnostic utility of such a biomarker." (PMID 37624696, 2023). "Analysis of AH from patients with glaucoma showed that SPP1 expression is also relevant to humans with glaucomatous neuropathy." (PMID 37624696, 2023). "Due to limited access to the retinal tissue of patients with glaucoma, we took advantage of the fact that SPP1 is a secreted protein that can be detected in aqueous humor (AH)." (PMID 37624696, 2023). "Because vitamin C induced neuroprotective astrocytes in vitro via SPP1, we further investigated the molecular mechanisms of vitamin C in astrocytes in vivo in a mouse glaucoma model." (PMID 37160307, 2023). "Furthermore, validation of the results directly with aqueous humor allowed us to identify GAS6 and SPP1 as relevant biomarkers for glaucoma diagnosis." (PMID 39000104, 2024).
glaucoma (continued). "Moreover, some studies have assessed SPP1 levels in primary open-angle glaucoma aqueous humor with opposite findings among them." (PMID 39000104, 2024). "Vitamin C protects retinal ganglion cells by upregulating SPP1 expression in glaucoma." (PMID 39845086, 2024). "In a model of glaucoma, a protective role for SPP1/OPN was found." (PMID 38646526, 2024). "Our study reveals Spp1’s role in mediating neuronal resiliency in glaucoma." (PMID 37624696, 2023). "SPP1+ astrocytes in turn promote retinal ganglion cell survival in a mouse model of glaucoma." (PMID 37160307, 2023). "Additionally, the secreted SPP1 concentrations in the aqueous humor of patients with glaucoma corresponded with disease severity." (PMID 37624696, 2023). "Finally, we analyzed the ability of GAS6 and SPP1 as glaucoma aqueous humor biomarkers to discriminate glaucoma patients from ICL and cataracts controls by ELISA using a collection of 162 individual aqueous humors samples (39 ICL, 92 cataracts, and 31 glaucoma samples)." (PMID 39000104, 2024). "Furthermore, these data illustrated that SPP1 may serve as an adult biomarker for disease progression in patients with glaucoma." (PMID 37624696, 2023). "Last, in the human ocular disease setting, the correlation of SPP1 levels with the severity of optic neuropathy in patients with glaucoma raises the possibility that SPP1 may be a relevant biomarker and a potential therapeutic target for glaucoma." (PMID 37624696, 2023). "Elevated SPP1 levels in aqueous humor may be biomarkers for human glaucoma progression." (PMID 37624696, 2023). "A patent in evaluation (P202430051) for glaucoma diagnosis based on the identification of GAS6 and SPP1 in aqueous humor resulted from the work reported in this manuscript." (PMID 39000104, 2024). "Individual areas under the curve (AUCs) for discriminating glaucoma patients from ICL or cataracts were 73% and 68.5% for GAS6 and 74.9% and 66.2% for SPP1, respectively." (PMID 39000104, 2024). "For SPP1, we obtained a mean concentration (pg/mL) of 14,063.73 in ICL samples, 16,080.71 in cataracts, and 24,279.04 in glaucoma patients." (PMID 39000104, 2024). "Vitamin C supplementation in the drinking water improved RGC survival, pattern ERG, and visual acuity in the glaucoma models of C57BL/6 and Spp1 KO mice, but vitamin C also significantly reduced the IOP itself." (PMID 37160307, 2023). "Additionally, SPP1 marked adult human RGC subsets with large somata and SPP1 expression in the aqueous humor correlated with glaucoma severity." (PMID 37624696, 2023).
glomerulonephritis (13 papers, 2007 to 2025). A renal disorder characterized by damage in the glomeruli. "It was reported that accumulation of macrophages (most likely increased expression of SPP1) promotes renal injury and fibrotic remodeling in glomerulonephritis." (PMID 37696527, 2023). "However, SPP1 can be expressed by ECs in other contexts, such as in glomerular capillaries during murine and human glomerulonephritis." (PMID 40114603, 2025).
Allergy (12 papers, 2010 to 2025). An allergy is an immune response or reaction to substances that are usually not harmful. "SPP1 is a phosphorylated acidic glycoprotein adhesion molecule that is frequently upregulated during event‐induced inflammation, including infection, trauma, allergy, and autoimmunity, performing biological functions through autocrine and/or paracrine signaling." (PMID 39939834, 2025).
gastric tumor (12 papers, 2011 to 2025). "Intriguingly, our western blotting showed obvious overexpression of SPP1 in gastric tumor tissues in the TCGA database, when compared to normal tissues." (PMID 34758833, 2021). "Importantly, our genomic expression profiles suggested that gastric tumor tissues exhibit aberrant overexpression of SPP1, which has been shown to be upregulated by YBX1 in renal cancer cells." (PMID 34758833, 2021). "The expression levels of CXCR4 and NFE2L2 as well as four differentially expressed NRGs (SPP1, CXCL1, MMP9, and TIMP1) were validated in gastric tumor cells and clinical samples." (PMID 38221932, 2024).
metastatic melanoma (12 papers, 2010 to 2025). A melanoma that has spread from its primary site to another anatomic site. "Binding of GLI1 to the SPP1 gene promoter was reported in metastatic melanoma cells indicating it could be a general feature of malignant cells." (PMID 28030801, 2017).
renal cell carcinoma (12 papers, 2015 to 2025). "Our previous research has demonstrated that YBX1 interacts with G3BP1 to upregulate its downstream protein SPP1 expression, thereby activating the NF-κB signaling pathway and thus promoting renal cell carcinoma (RCC) metastasis." (PMID 36330442, 2022). "Similarly, SPP1 expression was also found to be inversely correlated with CD8+ T cells in renal cell carcinoma." (PMID 39691723, 2024). "Cells from renal cell carcinoma (RCC) tissue in the dataset GSE167573 showed tumorous samples to have multiple exonic regions in several genes, among them SPP1 or ‘ENSG00000118785’ with five exons, S100A4 with two exons and CXCL12 with five exons." (PMID 39857756, 2025). "When comparing renal cell carcinoma (RCC) tissue samples from the dataset GSE151419 with increasing Fuhrman grades, there was a significantly large increase observed in SPP1 expression between grade 4 and grade 2 cancer-affected samples (log2FC = 1.590, p-value = 0.046)." (PMID 39857756, 2025).
cholangiocarcinoma (11 papers, 2016 to 2025). A carcinoma that arises from the intrahepatic biliary tree (intrahepatic cholangiocarcinoma) or from the junction, or adjacent to the junction, of the right and left hepatic ducts (hilar cholangiocarcinoma). "I-FLICE, MUC1, MMP14, mIDH1, and SPP1 were found to be highly expressed in cholangiocarcinoma tissues, and they promoted cholangiocarcinoma progression by affecting T cell interactions or T cell immune infiltration." (PMID 40070825, 2025). "CREB3L1, which is upregulated in S100P + SPP1− intrahepatic cholangiocarcinoma tumor cells, can facilitate the invasion of S100P + SPP1− perihilar large duct type tumor cells by directly targeting S100P." (PMID 36171879, 2022). "We further evaluated the effect of S100P and SPP1 in distinguishing iCCAphl and iCCApps in two RNA-seq databases of cholangiocarcinoma." (PMID 35347134, 2022).